Y_RNA (Y RNA )
Gene: Miscellaneous RNA gene on chromosome 8 (41,803,349 to 41,803,450, forward strand). Ensembl gene ENSG00000207101.
Homologues: Orthologues: chimpanzee Y_RNA (99% identical), macaque Y_RNA (95% identical), guinea pig Y_RNA (92% identical). Paralogues in human: Y_RNA (92% identical), RNY3 (91% identical), Y_RNA (91% identical), RNY3P1 (90% identical), Y_RNA (90% identical), Y_RNA (89% identical), Y_RNA (88% identical), RNY3P14 (87% identical), Y_RNA (87% identical), RNY3P11 (86% identical), RNY3P16 (86% identical), RNY3P5 (86% identical), and 96 more.